GDF15 (growth differentiation factor 15)
Diseases named in the same sentence as GDF15 in open-access papers (continued):
Sharing a sentence is not in itself a finding about the gene and the disease.
Cachexia (continued). "Furthermore, although GDF-15 did not associate with cachexia status/weight loss in NHB patients, it was associated with survival even when controlled for R&E." (PMID 39989973, 2025). "Additionally, elevated levels of growth differentiation factor 15 (GDF15) in cancer cachexia patients may be responsible for anorexia as recombinant GDF15 reduces food intake and promotes weight loss via anorexia." (PMID 38744744, 2024). "Therefore, GDF15 is now heavily investigated in cachexia because blocking GDF15 signaling may have the potential to counteract cachexia." (PMID 36902081, 2023). "Perhaps most excitingly, our work suggests that combining an anti-GDF15 antibody with chemotherapy could improve the overall survival of patients by the dual mechanisms of decreasing cachexia and either killing or preventing the development of DTPs during chemotherapy." (PMID 35626166, 2022). "In addition, GDF15 neutralization has robust efficacy in mitigating cachexia in this model." (PMID 35406637, 2022). "This study demonstrated an association between GDF15 levels and anorexia, suggesting that it could be an biomarker for anorexia rather than cachexia." (PMID 33925872, 2021). "However, anorexia and cachexia that should be caused by GDF-15-dependent activation of GFRAL are typically not observed during pregnancy, despite highly elevated GDF-15 serum levels." (PMID 32508832, 2020). "However, the recent use of monoclonal antibodies inhibiting GFRAL signaling reversed the GDF15-induced cachexia even under calorie-restricted conditions, revealing that GDF15 may lead to decreased adipose and muscle mass and function independently of anorexia." (PMID 33344478, 2020). "GDF15-GFRAL-RET regulates metabolic homeostasis, particularly under stress conditions, but may also promote cancer associated anorexia or cachexia, suggesting that blocking RET signals may have added benefit in reducing weight loss associated with other forms of therapy." (PMID 30666215, 2018). "Recently, several new cachexia-related factors, such as the growth factor GDF15 and the chemokine LCN2, which participate in cachexia through mechanisms that amplify inflammatory signals beyond traditional pathways, have been reported." (PMID 41526343, 2026). "Growth differentiation factor 15 (GDF15) is a cytokine and independent predictor of HF disease, mortality, and cachexia." (PMID 40738518, 2025). "GDF-15 and TNF-α perform better at cachexia classification than other commonly used classifiers of cachexia." (PMID 39989973, 2025). "The integration of morphofunctional assessment, including body composition at the T12 level, functional performance tests, and mitochondrial biomarkers such as GDF-15 and PGC-1α, enabled a more accurate classification of cachexia phenotypes." (PMID 40944130, 2025). "Further stratification by cachexia status for ENA-78/CXCL5, GRO-α /CXCL1 and GDF-15 (as a comparison) shows that ENA-78/CXCL5 and GRO-α/CXCL1 levels were unchanged for any R&E group when stratified by cachexia status." (PMID 39989973, 2025). "Circulating GDF15 and expression of GDF15 in tumour tissue have been shown to increase cancer related cachexia and novel data has shown GFRAL antagonism can reverse cachexia in mice." (PMID 40019842, 2025). "When TIMP-1 and GDF-15 levels were dichotomized using a median split, both TIMP-1 (P<0.001) and GDF-15 (P<0.001) were significantly increased over worsening cachexia status when subjected to a Cochrane-Armitage trend test." (PMID 39989973, 2025). "When cachexia status was classified using a 4-stage system 32, we find that patients with PCa can be differentiated from NCa patients by CRP, TIMP-1 and GDF-15." (PMID 39989973, 2025). "When ordinal regression was performed using cachexia status as the response variable and TIMP-1 and GDF-15 as predictor variables (dichotomized), GDF-15 remains significant as a predictor (P=0.021)." (PMID 39989973, 2025).
Cachexia (continued). "Elevated levels of growth differentiation factor 15 (GDF15) have been implicated in HG, as increased GDF15 levels under dietary stress may send an endocrine signal to the brain, triggering nausea, weight loss, and muscle wasting, similar to cachexia seen in tumor-bearing patients." (PMID 40843754, 2025). "The role of GDF15 is of particular interest in HNC, as patients frequently present with cachexia or malnutrition at diagnosis, either due to the disease itself or treatment-related sequelae." (PMID 40868185, 2025). "The mRNA was isolated from mouse kidneys and was used to examine the expression levels of signaling proteins, inflammatory cytokines, and genes responsible for inducing cachexia (IL-1β, IL-6, TNF-α, TGF-β, GDF-15, and MYD88)." (PMID 39394174, 2024). "Thereby, the GDF15/GFRAL/RET signaling pathway represents a potential therapeutic target for eating disorders, metabolic diseases and cancer-related cachexia." (PMID 38474863, 2024). "As our understanding of the genesis of cancer cachexia improves and more therapeutic options, ranging from basic (e.g. exercise and nutrition) to targeted (e.g. anti-IL1 α and anti-GDF-15), become available, there can be grounds for optimism." (PMID 36269458, 2022). "The main drivers of cachexia are cytokines such as interleukin-6 (IL-6), tumor necrosis factor-alpha (TNF-α), macrophage inhibitory cytokine 1 (MIC-1/GDF15) and transforming growth factor-beta (TGF-β)." (PMID 36078078, 2022). "Our results suggested the possible important role of GDF-15 in muscle atrophy of cancer cachexia and were consistent to previous reports about GDF15 in cachexia." (PMID 35379793, 2022). "The main cytokines driving cachexia are IL-6, TNF-α, TGF-β and MIC-1/GDF15 MIC-1/GDF15, a member of the TGF-β superfamily, is produced in large amounts by normal and cancer cells." (PMID 36078078, 2022). "We end this review with a discussion of three recently identified central mediators of cachexia, including GDF15, LCN2 and INSL3, all peripherally derived molecules that bind to their cognate receptors in the brain to drive cachexia symptoms." (PMID 34439145, 2021). "Interleukin-6 (IL6) and growth and differentiation factor 15 (GDF15), two BAT-secreted factors, are key mediators of cancer-induced cachexia." (PMID 34831253, 2021). "Thus, GDF15 may be useful as a biochemical marker to predict malnutrition and cachexia." (PMID 33178828, 2020). "Growth Differentiation Factor 15 (GDF15) is a stress-responsive cytokine that mediates anorexia and cachexia in many chronic diseases and cancer." (PMID 33344478, 2020). "A recent report on pharmacological GDF-15 administration to mice, which triggered conditioned taste aversion, also links GDF-15 more closely to anorexia than to cachexia and muscle wasting." (PMID 32508832, 2020). "Treatment of mice with GDF‐15 or implantation with a GDF‐15 overexpressing tumour is sufficient to induce cachexia, whereas treatment with a neutralizing antibody reversed cachexia in multiple murine cancer models." (PMID 32985801, 2020). "Despite the growing body of evidence that cachexia worsens morbidity and mortality in adults, no paediatric studies have assessed changes in GDF15 over time as predictors of morbidity and mortality." (PMID 40019842, 2025). "Overall, our findings suggest that, whereas non-Hispanic Whites and Hispanic/Latinx elevate circulatory GDF-15 levels in response to cachexia/metabolic stress, NHB do not." (PMID 39989973, 2025). "In the case of cancer cachexia, LIF acts in concert with a number of other catabolic factors (IL-6, TNF-α, GDF15, etc.)that may amplify signals of muscle-wasting." (PMID 40869331, 2025). "In summary, GDF-15/GFRAL antagonism may offer multiple therapeutic benefits, including anti-cachexia effects, potential relief of CINV, and enhanced immunotherapy." (PMID 41294666, 2025). "Most importantly cachexia was not apparent in these models, so the role of GDF15 was not examined in this context." (PMID 39312445, 2024).
Cachexia (continued). "Growth differentiation factor-15 (GDF-15) has an important role in cachectic patients, as high levels of GDF-15 in the early stages of cachexia represent a poor prognostic factor for patients who experienced weight loss and its overexpression stimulates muscle atrophy." (PMID 38067294, 2023). "GDF15 was reported to be elevated in MCT-treated rats, a cardiac cachexia model, suggesting it might play a role in the development of cachexia induced by MCT." (PMID 35406637, 2022). "The cachexia markers IL6 and GDF15 differ between ages in both mice and patients." (PMID 35008253, 2021). "Indeed, just the past 2 years of research identified GDF15, Lipocalin 2 (LCN2) and insulin-like 3 peptide (INSL3) as novel peripherally derived factors that activate CNS circuitry to drive cachexia symptoms." (PMID 34439145, 2021). "In addition to high circulating levels of MIC-1/GDF15 mediating anorexia/cachexia in disease states, this study demonstrates that changes in MIC-1/GDF15 in the physiological range modifies feeding behavior and body weight in mice." (PMID 23468844, 2013). "Indeed, for non-NHB patients, our findings suggest that GDF-15 is a marker for early cachexia and that IL-6 increases at a later stage in the cachectic continuum (i.e. when the patient has refractory disease)." (PMID 39989973, 2025). "Thus, it is possible that a subset of patients with pre-cachexia and elevated GDF-15 do not go on to develop cachexia." (PMID 39989973, 2025). "It is hypothesized that cachexia in many types of cancer, including NSCLC, CRC and PANC, is largely mediated via GDF‐15 and that suppression of GDF‐15 may improve cachexia‐related symptoms, including anorexia, leading to unintended weight loss, fatigue and impaired mobility." (PMID 38500292, 2024). "Furthermore, patients that fitted the criteria for cachexia, exhibited greater plasma GDF15 than those that did not fit the criteria." (PMID 39312445, 2024). "In addition, experiments have shown that circulating GDF15 levels in tumor patients with cachexia are significantly higher than those in tumor patients without cachexia." (PMID 36105371, 2022). "Neither IL6 nor GDF15 therefore seem to be universal cachexia biomarkers in mouse models." (PMID 35008253, 2021). "However, anorexia and cachexia, which would be expected at high GDF15 levels, does not normally occur during pregnancy." (PMID 34043633, 2021). "GDF15 mAb2 treatment does not prevent MCT-induced cardiac dysfunction, indicating that the efficacy on cachexia prevention is independent of cardiac function in this model." (PMID 35406637, 2022). "In rodents, SNS denervation or β-adrenergic receptor antagonists attenuate GDF-15-mediated catabolic conditions without directly inhibiting GDF-15, demonstrating the involvement of neural pathways in GDF-15-induced cachexia via the central and peripheral nervous systems." (PMID 41294666, 2025).
atherosclerosis (118 papers, 2012 to 2026). A disease characterized by the build-up of fatty material and calcium deposition in the arterial wall resulting in partial or complete occlusion of the arterial lumen. "Despite inconsistencies in published findings, most studies suggest an association between elevated GDF-15 and subclinical or progressive atherosclerosis, as well as with cardiovascular outcomes." (PMID 41597417, 2026). "Confounders such as age, renal impairment, chronic inflammation, metabolic dysfunction, and cardiovascular risk remain key determinants in GDF-15’s involvement in both cardio–reno–metabolic disorders and atherosclerosis." (PMID 41597417, 2026). "After adjustment for confounders, the strength of the association between GDF-15 and atherosclerosis diminishes, and in some cases the statistical significance is lost." (PMID 41597417, 2026). "In most of the studies, the association between GDF-15 and markers of subclinical atherosclerosis was positive, and directly correlated with atherosclerotic burden." (PMID 41597417, 2026). "Across metabolic conditions, GDF-15 was associated with multiple markers of subclinical atherosclerosis, such as ABI, CIMT, or FIMT." (PMID 41597417, 2026). "The role of GDF15 in CV disease is further supported by a recent study reporting an association between subclinical atherosclerosis and a GDF15 single-nucleotid polymorphism (SNP) related to increased circulating levels of this stress-response cytokine." (PMID 40076667, 2025). "This is particularly evident in atherosclerosis, where plaque-associated macrophages demonstrate notable GDF15 induction." (PMID 40837873, 2025). "Growth differentiation factor 15 (GDF15), a stress-responsive cytokine implicated in inflammation, atherosclerosis, and thrombosis, has been broadly studied in cardiovascular disease but remains underexplored in PAD." (PMID 40723863, 2025). "In the present study, fast eating speed was significantly positively associated with atherosclerosis, but only in participants with a high GDF-15 level." (PMID 39019981, 2024). "Since p < 0.2 for interaction is considered to be statistically significant, this study demonstrated a significant interaction of GDF-15 level on the association between fast eating speed and atherosclerosis." (PMID 39019981, 2024). "In the present study, only participants with a high GDF-15 level exhibited a significant positive association between fast eating speed and atherosclerosis." (PMID 39019981, 2024). "The major finding in this study of participants with normal thyroid hormone ranges was that fast eating speed was positively associated with atherosclerosis, but only in individuals with a high GDF-15 level." (PMID 39019981, 2024). "This is the first study to reveal a positive association between fast eating speed and atherosclerosis in a general population, and to demonstrate the influence of GDF-15 level on this correlation." (PMID 39019981, 2024). "The aim of this study was to assess the impact of selected GDF15 single-nucleotide polymorphisms (SNPs) on metabolic disturbances and subclinical atherosclerosis." (PMID 39596055, 2024). "Fast eating was associated with high odds of atherosclerosis but only among participants with a high GDF-15 level." (PMID 39019981, 2024). "In conclusion, in a general elderly population, GDF-15 level was a determinant of the association between fast eating speed and atherosclerosis." (PMID 39019981, 2024). "The potential anti-inflammatory effect of GDF-15 is also associated with its possible protective effect against atherosclerosis." (PMID 38255954, 2024). "Atherosclerotic mouse models have shown a causal role of GDF15 in the chemotaxis of macrophages to the plaque, specifically during the early phase of atherosclerosis." (PMID 39780955, 2024). "Even after adjusting for high levels of both, a significant positive association between fast easting speed and atherosclerosis was observed only in participants with a high GDF-15 level." (PMID 39019981, 2024).
atherosclerosis (continued). "In the high GDF-15 group only, fast eating speed was significantly positively associated with atherosclerosis." (PMID 39019981, 2024). "This is the first study that revealed a positive association between serum GDF-15 concentration and atherosclerosis as evaluated by CIMT among older individuals with normal weight and thyroid hormone levels." (PMID 37371667, 2023). "In conclusion, among older individuals with normal weight and normal thyroid hormone levels, the serum GDF-15 concentration was revealed to be significantly positively associated with atherosclerosis." (PMID 37371667, 2023). "A significant positive association between serum GDF-15 concentration and atherosclerosis was observed." (PMID 37371667, 2023). "The major finding of the present study is that GDF-15 is positively associated with atherosclerosis as evaluated by CIMT among general older Japanese individuals with normal weight, independent of thyroid function and known cardiovascular risk factors." (PMID 37371667, 2023). "that shows that increased circulating GDF15 levels were closely associated with cardiovascular diseases and were shown to be a strong marker of disease progression in patients with atherosclerosis." (PMID 35846052, 2022). "We selected disease endpoints showing association to the GDF15 plasma levels, namely type 2 diabetes, atherosclerosis (excluding cerebral, coronary, and PAD), COPD, psychiatric disorders, and malignant neoplasm of respiratory system and intrathoracic organs." (PMID 35916366, 2022). "CIMT (as a marker of subclinical atherosclerosis) is increased in these patients alongside with GDF‐15, is a predictor, and associated with atherosclerosis in thalassemic adults." (PMID 35846052, 2022). "So, GDF‐15 is associated with atherosclerosis in adults with transfusion dependable beta‐thalassemia." (PMID 35846052, 2022). "So, we found that GDF‐15 is a predictor of and associated with atherosclerosis in thalassemic adults (OR = 39.198, p value 0.008, 95% CI: 2.576–596.5)." (PMID 35846052, 2022). "Stenosis of blood vessels due to development of atherosclerotic plaques is a hallmark of atherosclerosis; thus, we investigated the effect of the GDF-15 deficiency on the development and progression of the atherosclerotic lesions in the PT and BT." (PMID 34920697, 2021). "One previous atherosclerosis mouse model study demonstrated that GDF-15 deficiency attenuates early atherogenesis and improves plaque stability." (PMID 34539804, 2021). "Previously, we have shown that GDF-15 is a factor implicated in several pathophysiological processes including autophagy, inflammation, chronic vascular diseases, cancer, ischemia, and atherosclerosis." (PMID 34920697, 2021). "This study suggested that GDF-15 is possibly associated with atherosclerosis and can play a protective role." (PMID 34539804, 2021). "Here, we proved the effect of GDF-15 of autophagy by using, in vitro, a human atherosclerosis MΦ model and in vivo GDF-15-deficient (GDF-15−/−) mice within an experimental atherosclerosis apolipoprotein (apo)E knockout (ApoE−/−) mouse model." (PMID 34571994, 2021). "Pleiotropic roles of GDF15 have been implicated in both pro‐ and anti‐inflammation throughout the progression of atherosclerosis." (PMID 32157804, 2020). "GDF-15 is associated with e.g. cardiovascular disease, inflammation and development of atherosclerosis and is highly expressed in macrophages (MΦ) of atherosclerotic lesions." (PMID 31372395, 2019). "Another supporting evidence for the protective role of GDF15 on atherosclerosis came from a study using ApoE deficient mouse model of atherosclerosis." (PMID 30542297, 2018). "MIC-1/GDF15 has been associated with cardiovascular events, in which atherosclerosis is the most common underlying pathological mechanism." (PMID 25867953, 2015). "They explained that GDF-15 deficiency results in inhibition of atherosclerosis progression in hypercholesterolemic mice." (PMID 26075263, 2015).